GLUD1 (glutamate dehydrogenase 1)
Diseases named in the same sentence as GLUD1 in open-access papers (continued):
Sharing a sentence is not in itself a finding about the gene and the disease.
pancreatic cancer (10 papers, 2015 to 2025). "Higher GLUD1 expression was detected in pancreatic tumors compared to paired adjacent tissues, as well as in recurrent pancreatic cancers compared to non-recurrent cases." (PMID 40487432, 2025). "Son and his colleagues had proved that GOT1 mediates the utilization of glutamine in pancreatic cancer; oncogenic KRAS coordinates the shift from canonical type to non-canonical type of glutamine-dependent metabolism by increasing expression of GOT1 and decreasing expression of GLUD1." (PMID 25719198, 2015). "Additionally, PCSCs carrying shControl, shGLUD1, and shGOT1#2 were subjected to 2 weeks of culture with fractional IR treatment, and suppression of GOT1—but not GLUD1—significantly increased radiosensitivity in PCSCs from both pancreatic cancer cell lines." (PMID 26439804, 2015). "GLUD1 inhibition might be ineffective in pancreatic cancer, since oncogenic KRASG12D has been suggested to inhibit GLUD1 and preferentially activate the noncanonical glutaminolysis pathway." (PMID 32947972, 2020).
schizophrenia (10 papers, 2012 to 2024). A major psychotic disorder characterized by abnormalities in the perception or expression of reality. "We also found that the SCHEMA schizophrenia M3 variant GluD1-A650T produced constitutively active receptors." (PMID 37944084, 2024). "A study found a significant post-mortem reduction in Glud1 expression in the CA1 subregion associated with schizophrenia." (PMID 37298365, 2023). "We think it is also worth noting that the Glud1 gene is associated with susceptibility to schizophrenia, autism, depression and bipolar affective disorder." (PMID 37298365, 2023). "GDH is encoded by Glud1, and Glud1-deficient mice have behavioural abnormalities that are characteristic of schizophrenia." (PMID 37298365, 2023). "Human GluD1 gene (GRID1) is a gene associated with susceptibility to schizophrenia, autism spectrum disorder, and depression." (PMID 32078638, 2020). "The GluD1 gene is associated with susceptibility for schizophrenia, autism, depression, and bipolar disorder." (PMID 32078638, 2020). "The gene encoding GluD1 in humans (GRID1) is associated with a susceptibility for schizophrenia, major depressive disorder, and autism spectrum disorder." (PMID 32078638, 2020). "Our expression results indicating a potential excitatory-inhibitory imbalance also support association of GluD1 with ASDs and schizophrenia where hypofunctioning of GABAergic system has been demonstrated." (PMID 23560106, 2013). "Since GRID1 gene has been found to be associated with schizophrenia we tested latent inhibition in GluD1 KO mice." (PMID 23560106, 2013). "As previously stated, the GRID1 gene that codes for GluD1 is strongly associated with mental disorders including schizophrenia, bipolar disorder, ASD and major depression." (PMID 22412961, 2012). "GLUD1, which plays a role at glutamatergic synapses, has been implicated in schizophrenia." (PMID 26113971, 2015). "Genetic association and genome wide association studies indicate that the dysregulation of GluD1 may play a role in neuropsychiatric conditions such as schizophrenia, bipolar disorder, major depressive disorder and autism spectrum disorders (ASDs)." (PMID 23560106, 2013). "Similarly, contextual and cue fear conditioning deficits in GluD1 knockout mice also occur in mice models implicated in ASDs and schizophrenia and may represent impaired conditioned association in schizophrenic and ASD individuals." (PMID 23560106, 2013). "This is the first demonstration of a gene x environment interaction in mice with abnormal expression of Glud1, which is downregulated in schizophrenia and predicts antipsychotic treatment efficacy." (PMID 37419882, 2023). "In vivo study have demonstrated the coupling of glutamate metabotropic receptor 1/5 and GluD1 is essential to the firing of dopamine neurons in the midbrain that are correlated with the physiopathology of schizophrenia." (PMID 38075685, 2023). "Genetic association studies have established the GRID1 gene, which codes for GluD1, as a strong candidate gene for schizophrenia, bipolar disorder, and major depressive disorder." (PMID 22412961, 2012). "Interestingly, lower GluD1 expression has been reported in the cortex of human patients with schizophrenia, bipolar disorder and ASD." (PMID 22412961, 2012). "Interestingly, excitatory-inhibitory imbalance in prefrontal cortex and amygdala have been reported in schizophrenia and ASD animal models, disorders with which GluD1 has been associated." (PMID 22412961, 2012). "Whether such modulators would be directly relevant to pharmacotherapy is unclear, as the links between low GluD1 expression and schizophrenia and GluD2 overactivity and cerebellar ataxia may pertain to early development (51, –53) and thus be inaccessible to pharmacotherapy." (PMID 38285949, 2024). "GluD1 associated disorders including ASD, schizophrenia and bipolar disorder have several overlapping negative symptoms and cognitive deficits and may have a common genetic link." (PMID 23560106, 2013).
hepatocellular carcinoma (9 papers, 2015 to 2025). A malignant tumor that arises from hepatocytes. "The treatment of hepatocellular carcinoma with N-acetylcysteine (NAC) has been shown to impede GLUD1 activation and mitochondrial apoptosis via the ROS-mediated p38/JNK MAPK pathway." (PMID 40598593, 2025). "Previously, we found GLUD1 was down-regulated in tumor tissues of hepatocellular carcinoma (HCC) patients by proteomics study." (PMID 38216781, 2024). "Specifically, GLUD1 is overexpressed in certain malignancies, such as non-small cell lung cancer (NSCLC); while it is downregulated in hepatocellular carcinoma (HCC) and clear cell renal carcinoma." (PMID 40710547, 2025). "However, little is known about the relationship between GLUD1 and hepatocellular carcinoma (HCC)." (PMID 38587834, 2024). "Hepatocellular carcinoma (HCC), one of the most lethal cancer and which requires the continuous development of new therapeutic strategies, shows an up-regulation of human glutamate dehydrogenase 1 (hGDH1)." (PMID 34829892, 2021).
depression (8 papers, 2012 to 2025). "While little is known about the phenotypic features of GRID1 human variants, GluD1 knock-out mice exhibit social deficits, in addition to anxiety-like, depression-like and aggressive behaviors." (PMID 37944084, 2024). "hsa-miR-16a-5p targets BDNF, NPY4R, and GLUD1, which have been reported to be involved in the pathophysiology of anxiety and depression." (PMID 39821903, 2025). "Deletion of GluD1 in mice leads to hyperactivity, social deficits, aggression and depression-like behavior, as well as deficits in learning and memory." (PMID 37944084, 2024). "It is also worth noting that impaired fear memory and social interactions and the reinforcement of depression-like behaviours were observed in GluD1 gene knockout mice." (PMID 37298365, 2023). "GluD1 gene knockout mice show impaired fear memory and social interactions and enhanced depression-like behaviour." (PMID 37298365, 2023). "Next, we tested the impact of representative antidepressants on depression-like behavior in GluD1-KO mice." (PMID 32078638, 2020). "Candidate regions, in which GluD1 is expressed, related to depression are the lateral habenula and dorsal raphe nucleus." (PMID 32078638, 2020). "We also observed higher expression of PSD95 in the amygdala in GluD1 knockout which correlates with elevated PSD95 reported in lateral amygdala in patients suffering from depression." (PMID 22412961, 2012). "In this study we performed behavioral characterization of the GluD1 KO mice and found remarkable features including hyperactivity, lower anxiety-like behavior, depression-like behavior, hyperaggression and deficits in social interaction in the GluD1 KO." (PMID 22412961, 2012). "Since, hyperaggression- and depression-like behavior in the GluD1 KO mirror some aspects of bipolar disorder, we tested the effect of chronic lithium on these behaviors." (PMID 22412961, 2012). "In particular, we observed that deletion of GluD1 led to hyperactivity, lower anxiety-like behavior, depression- and aggression-like behavior and social interaction deficits." (PMID 22412961, 2012). "One of the unique features of GluD1 knockout was the presence of both depression- and aggression-like behaviors which mirror some features of bipolar disorder-like behavior." (PMID 22412961, 2012). "We performed a set of experiments to further test for locomotor activity, anxiety-like behavior, depression- and aggression-like behaviors and social interaction, in GluD1 KO mice." (PMID 22412961, 2012). "We found that GluD1 knockout mice (GluD1 KO) were hyperactive, manifested lower anxiety-like behavior, depression-like behavior in a forced swim test and robust aggression in the resident-intruder test." (PMID 22412961, 2012). "Furthermore, GluD1 mRNA is downregulated in the frontal cortex of anhedonic rats as an animal model of depression, and this phenotype is completely reversed by intraperitoneal injection of the antipsychotic quetiapine." (PMID 32078638, 2020). "GluN2B selective inhibitor and partial agonist of GluN2B-containing receptors reversed the abnormality in cofilin signaling, spine density, as well as several behavioral phenotypes including depression-like behavior, repetitive behavior and social deficit in GluD1 KO21,26." (PMID 30315226, 2018). "Synaptic regulation and glutamate signaling mediated by GluD1 may influence the development of schizophrenia and depression-related symptoms." (PMID 25762938, 2015). "Thus lithium was able to rescue depression-like behavior in GluD1 KO." (PMID 22412961, 2012). "Additionally, in a chronic mild stress model of depression-like behavior in rats, GluD1 mRNA in the frontal cortex is downregulated and this could be completely reversed by the antipsychotic quetiapine." (PMID 22412961, 2012). "Interestingly, the occurrence of both mania- and depression-like behaviors suggests that GluD1 knockout may have some face validity for bipolar-like behavior." (PMID 22412961, 2012).
depression (continued). "GluD1-KO mice showed hyperactivity in the OFT, decreased anxiety-like behavior in the EPM and marble burying tests, depression-like behavior and anhedonia in the FST and SPT, and increased aggressive behavior." (PMID 25762938, 2015). "To avoid these issues, we generated GluD1-KO mice with a pure C57BL/6N genetic background and investigated an impact of GluD1 deletion on various behaviors including anxiety, aggression, sensorimotor gating, sociability, learning and memory, and depression." (PMID 32078638, 2020).
Hypoglycemia (8 papers, 2008 to 2025). A decreased concentration of glucose in the blood. "Finally, in two additional patients (11.1%) with GSD Ib and GLUD-1 deficiency, postprandial hypoglycemia was observed." (PMID 39861352, 2025). "Therefore, due to the loss of inhibitory control of GDH by mutations in GLUD1, insulin was secreted excessively under basal conditions as well as after protein meals, triggering hyperinsulinemia and hypoglycemia." (PMID 36721237, 2023). "The GLUD1 gene was detected in patients with hypoglycaemia, HI and mild HA." (PMID 31208162, 2019). "Interestingly, ammonium accumulation and occasionally hypoglycemia have been reported in a rat 3D brain cell model of GA1 and in GA1 children, respectively, supporting a potential functional interaction between Glud1 and GCDH." (PMID 24498361, 2014).
Anxiety (6 papers, 2012 to 2025). Intense feelings of nervousness, tension, or panic often arise in response to interpersonal stresses. "Based on the results of the time spent in the central square of the open field arena we found that GluD1 KO mice display a trend for lower anxiety-like behavior." (PMID 22412961, 2012). "To determine whether GluD1 was involved in anxiety-related behavior, we performed tests in an open field, an elevated plus maze, and a light-dark transition test." (PMID 32078638, 2020). "The deficit in fear acquisition in GluD1 knockout is therefore in agreement with our previous findings showing that GluD1 knockout exhibit lower anxiety-like behavior in the plus maze test and abnormalities in expression of synaptic proteins in the amygdala and hippocampus." (PMID 23560106, 2013). "Although the parameter of number of entries may be confounded by hyperactivity which was observed with GluD1 KO in the open field test, overall these results suggest that GluD1 KO mice manifest lower anxiety-like behavior." (PMID 22412961, 2012). "These behaviors may be consistent with the phenotypic features of this patient with GluD1-R341Q, which include intellectual disability, ADHD, aggression, anxiety, and schizoaffective disorder." (PMID 37944084, 2024). "Furthermore, miR-16-5p was predicted to target to BDNF, NPY4R, GLUD1, and FKBP5, which are reported to be involved in the pathophysiology of anxiety and depression." (PMID 33737514, 2021).
colorectal cancer (5 papers, 2016 to 2025). A primary or metastatic malignant neoplasm that affects the colon or rectum. "SIRT5 supports the anaplerotic entry of glutamine into the tricarboxylic-acid (TCA) cycle in malignant phenotypes of colorectal cancer (CRC) via activating glutamate dehydrogenase 1 (GLUD1)." (PMID 35915188, 2022). "Taken together, colorectal cancer cells that can adapt to nutritional stress via regulation of GLUD1 and SLC25A13 contribute to tumor aggressiveness and result in worse prognosis." (PMID 27924922, 2016). "Taken together, the present study showed that GLUD1 was important in resistance to glucose-deprived conditions in colorectal cancer." (PMID 27924922, 2016). "GLUD1 and SLC25A13 have pivotal roles in nutritional stress and are associated with tumor aggressiveness and poorer prognosis of colorectal cancer." (PMID 27924922, 2016). "GLUD1 and SLC25A13 were associated with tumor aggressiveness and poorer prognosis of colorectal cancer." (PMID 27924922, 2016). "Glutamate dehydrogenase 1 (GLUD1) and SLC25A13 have pivotal roles under glucose-deprived conditions and are associated with tumor aggressiveness and colorectal cancer prognosis." (PMID 27924922, 2016). "Studies have reported that GLUD1 is overexpressed in lung and colorectal cancers." (PMID 35847357, 2022). "Subsequently, the relevance of GLUD1 and SLC25A13 expression in colorectal cancer with respect to clinicopathological characteristics and prognosis was evaluated by immunohistochemistry." (PMID 27924922, 2016). "In conclusion, GLUD1 and SLC25A13 may serve as new targets in treating refractory colorectal cancer which survive in malnutritional microenvironments." (PMID 27924922, 2016). "The experimental data indicated that the GLUD1 expression was independent of PKM2 expression, supporting the notion that both glucose metabolism and glutamine metabolism are important for the colorectal cancer." (PMID 27924922, 2016).
Intellectual disability (5 papers, 2024 to 2026). "The GluD1 interaction network and its downstream target genes are closely linked to the pathogenesis of intellectual disability (ID) and autism spectrum disorders (ASDs)." (PMID 41515947, 2025). "Several genetic and knockdown studies have shown that GluD1 plays an important role in these diseases, such as schizophrenia, bipolar I disorder, autism spectrum disorders (ASDs), and intellectual disability (ID)." (PMID 41515947, 2025). "Finally, human genetic studies revealed the relationship of GluD1 with neuropsychiatric disorders, including schizoaffective disorders and intellectual disability, which is consistent with the phenotypes observed in mice upon GluD1 ablation." (PMID 41636022, 2026).
prostate carcinoma (4 papers, 2007 to 2026). A carcinoma that arises from epithelial cells of the prostate gland. "Targeting α-KG-metabolizing enzymes, such as IDH1 or GLUD1, presents promising therapeutic strategies for prostate cancer subtypes by inhibiting tumor proliferation and inducing oxidative stress, thus sensitizing tumors to ferroptosis." (PMID 42225654, 2026).
Alzheimer disease (3 papers, 2015 to 2024). A progressive, neurodegenerative disease characterized by loss of function and death of nerve cells in several areas of the brain leading to loss of cognitive function such as memory and language. "These mouse model data indicate that not only HI/HA syndrome but also age-related disorders such as Alzheimer’s disease could be associated with the GLUD1 mutations." (PMID 38673928, 2024). "A study of a mouse model with GLUD1 overexpression in neurons has observed degeneration of the CA1 hippocampal region, resembling Alzheimer’s disease pathology." (PMID 38673928, 2024).
astrocytomas (3 papers, 2021 to 2025). "In contrast, GLUD1 may lead to a decrease in GSH synthesis in IDH1mut low-grade astrocytomas increasing the susceptibility to oxidative stress, rendering them more sensitive to radiation therapy and to alkylating therapy." (PMID 33910646, 2021). "The expression levels of GLUD1, GOT1, GOT2, and GPT2 were differentially expressed in astrocytomas compared to NN (p < 0.0001 Kruskal–Wallis test for GLUD1, GOT1, and GPT2 and p < 0.002 for GOT2)." (PMID 33910646, 2021). "Interestingly, in lower-grade astrocytomas with IDH1 mutations, higher GLUD1 and GPT2 expression correlates with lower GSH levels, potentially increasing sensitivity to oxidative stress and treatments like radiation therapy." (PMID 41009025, 2025). "As astrocytomas increase in malignancy, GSH levels rise, potentially due to the downregulation of GLUD1 and GPT2, leading to increased glutamate availability for GSH synthesis." (PMID 41009025, 2025). "GLUD1 expression was shown to be downregulated in GBM, and upregulated in lower grades of astrocytoma (AGII-AGIII)." (PMID 37100462, 2023). "Expression analysis of transcript coding for the key enzymes involved in glutaminolysis, GLSiso1, GLSiso2, GLS2, GLUD1, GOT1, GOT2, and GPT2 was performed in our series of astrocytomas of different malignant grades and NN brain samples." (PMID 33910646, 2021). "Significant downregulation of GLUD1 and GPT2 expressions were observed in GBM compared to lower-grade astrocytoma in our cohort and confirmed in the TCGA dataset." (PMID 33910646, 2021).
Hypertension (3 papers, 2012 to 2025). The presence of chronic increased pressure in the systemic arterial system. "The proteomic response that contributes to the SHR phenotype and reduction of hypertension in Taichong-needled rats includes the modulation of seven proteins related to oxidative stress, including SOD, ALDH2, GSTM5, GLUD1, protein DJ-1, HSP90α, and α-ETF." (PMID 22984478, 2012). "In our previous study, the proteomic response that contributes to the SHR phenotype and reduction of hypertension in LR3-needled rats includes the modulation of seven proteins related to oxidative stress in the medulla oblongata, including SOD, ALDH2, GSTM5, GLUD1, protein DJ-1, Hsp90a, and a-ETF." (PMID 29853959, 2018).
liver cancer (3 papers, 2022 to 2024). An epithelial or non-epithelial malignant neoplasm that arises from the liver. "In this study, we show that BET inhibition induces MYC-independent and glutamate dehydrogenase 1 (GDH1)-dependent glutamine metabolic remodeling in liver cancer." (PMID 39872506, 2024). "Moreover, we presented novel mechanisms for LASP1 and SYVN1 to be involved in HBX-mediated GLUD1 inhibition in HBV-induced liver cancer." (PMID 38587834, 2024). "Notably, our investigation of the biological role of GLUD1 was dependent on liver cancer lines." (PMID 38587834, 2024). "The significance of HBX in triggering the transformation of normal hepatocytes to cancer cells and promoting the development of HBV-positive liver cancer has been studied, but whether HBX regulates GLUD1 to promote hepatocarcinogenesis remains to be determined." (PMID 38587834, 2024).